CTLA4 (cytotoxic T-lymphocyte associated protein 4)
Diseases named in the same sentence as CTLA4 in open-access papers (continued):
Sharing a sentence is not in itself a finding about the gene and the disease.
autoimmune disease (continued). "IKAROS and CTLA4 deficiencies are inborn errors of immunity and show similar clinical phenotypes, including hypogammaglobulinemia and autoimmune diseases (ADs)." (PMID 35087518, 2021). "Variants of human CTLA4 are associated with a wide range of autoimmune diseases, including SLE, RA, T1DM, GD, and MS." (PMID 34484216, 2021). "Despite the considerable contribution of variants in the CTLA4-ICOS intergenic region to autoimmune diseases, its role has remained unappreciated in SLE." (PMID 34736521, 2021). "CTLA-4 is an important negative regulator of the immune system, exhibiting several polymorphisms associated with susceptibility to autoimmune diseases." (PMID 34506591, 2021). "In autoimmune disease, Programmed Cell Death 1 (PD-1), PD-1 ligand (PD-L1), and Cytotoxic T-lymphocyte-associated protein 4 (CTLA-4) are now well recognized as co-inhibitory molecules able to brake and modulate the immune response." (PMID 33255336, 2020). "The SNP rs3087243 in CTLA4 is associated with several autoimmune diseases, including SLE, RA, T1D, and Graves' disease." (PMID 32328064, 2020). "According to the literature, common CTLA-4 polymorphisms have been found to confer susceptibility to T1D, AITDs and other autoimmune disorders." (PMID 32974248, 2020). "In various previous studies, the CTLA-4 rs5742909-T allele has been associated with a lower risk of suffering from autoimmune diseases such as RA, systemic lupus erythematosus or Graves’ disease." (PMID 33187286, 2020). "Increasing reports of allelic association between specific polymorphisms of CTLA-4 gene with various autoimmune diseases support the idea that the CTLA-4 region is an important locus for autoimmune disease in general." (PMID 32148437, 2020). "The GG genotype of this SNP was shown to represent a risk modulator for autoimmune diseases possibly due to the G allele dependent transcriptional downregulation of CTLA4." (PMID 33059697, 2020). "Recent research revealed that the T cells of LRBA (lipopolysaccharide-responsive and beige-like anchor protein)-deficient patients undergo accelerated CTLA-4 protein degradation, leading to life-threatening infiltration and autoimmune diseases." (PMID 32724457, 2020). "The polymorphisms associated with the CTLA-4 gene have also been investigated for their association with the risk of developing autoimmune diseases." (PMID 33187286, 2020). "Single‐nucleotide polymorphisms in CTLA‐4 have been correlated with a variety of autoimmune diseases, such as rheumatoid arthritis, systemic lupus erythematosus, inflammatory bowel disease, type 2 diabetes, and rheumatoid arthritis." (PMID 32621335, 2020). "While these immunotherapies have shown striking success, blockade of CTLA-4 and PD-1/PD-L1 are associated with adverse effects that resemble autoimmune disorders, including SLE, RA, thyroiditis, and T1D." (PMID 33251233, 2020). "The use of anti–PD-1, anti–PD-L1, or anti–CTLA-4 antibodies in patients with concomitant autoimmune disease is a procedure with a high risk of complications, therefore, it is not recommended to choose this type of treatment as adjuvant therapy." (PMID 33330040, 2020). "For example, in terms of genetic associations, CTLA-4 polymorphisms have been linked to an increased risk of autoimmune diseases, such as type 1 diabetes, and preclinical models have shown that anti-CTLA-4 can increase the risk of autoimmune diabetes." (PMID 32796758, 2020). "PD-1-deficient mice develop autoantibody-induced disease in a strain-dependent fashion; this autoimmune disease includes lupus-like glomerulonephritis leading to late death, although the phenotype in these mice is much milder than that of CTLA4-deficient mice." (PMID 33251233, 2020). "Both, the PTPN22 rs2476601 and CTLA4 rs3087243 SNPs were shown to be associated with numerous autoimmune diseases, including T1D, SLE, and RA." (PMID 32328064, 2020).
autoimmune disease (continued). "The deletion of the CTLA‐4 haplotype can cause autoimmune diseases, multiorgan invasion by lymphocytes, and the peripheral B cells and immunoglobulin deficiency." (PMID 32621335, 2020). "CTLA-4 is a negative regulator of T-cell responses and has been implicated in various autoimmune diseases." (PMID 31998632, 2019). "Due to single nucleotide polymorphisms (SNP) in the CTLA-4 gene, regulation of the amount of the different splice variants is altered, leading to an increased susceptibility to several autoimmune diseases." (PMID 31177287, 2019). "For example, for the −318T/T and +49AA genotype, an increased expression of cell-surface CTLA-4 was detected and was associated with a reduced susceptibility to autoimmune diseases." (PMID 31177287, 2019). "In humans, inactivating CTLA-4 (i.e., ipilimumab) is linked with a wide array of autoimmune disorders including thyroiditis." (PMID 31412566, 2019). "An abnormal expression of the CTLA-4 gene has been connected with an increased risk of several autoimmune diseases, like rheumatoid arthritis, infectious diseases, transplantation, and asthma." (PMID 31177287, 2019). "The use of Ipilimumab, a CTLA-4-blocking antibody, was reported to cause inflammatory exacerbation in 25% of patients who had preexisting autoimmune diseases." (PMID 31824865, 2019). "In humans, polymorphisms in the CTLA4 and PD-1 gene confer increased susceptibility to a variety of autoimmune disorders, including T1D." (PMID 31330498, 2019). "The immune dysfunction would be affected by CTLA4 genetic variation, and the risk of cancer and the development of autoimmune disease would be increased." (PMID 31684013, 2019). "James P. Allison and other research teams have worked to elucidate the biological role of cytotoxic T lymphocyte-associated protein 4 (CTLA-4) in the treatment of several cancers and autoimmune diseases models." (PMID 31683894, 2019). "Studies from European descendents demonstrated that CT60 in the 3′-UTR of CTLA-4 gene was the most likely causal locus in susceptibility to autoimmune diseases, including type 1 diabetes." (PMID 29973665, 2018). "In fact, some association studies indicated that there is an association between several CTLA-4 gene polymorphisms and various autoimmune diseases." (PMID 29850619, 2018). "It seems likely that the finding of clustering of autoimmune diseases in individuals is contributed to by shared genetic susceptibility loci at immune regulatory genes (HLA, CTLA-4, PTPN22 and CD40)." (PMID 29529281, 2018). "+49A>G SNP is a CTLA-4 gene polymorphism which is probably the most widely studied and most commonly associated with autoimmune disorders and cancers." (PMID 29850619, 2018). "Common single nucleotide polymorphisms (SNPs) in CTLA-4 have been found to have a role in susceptibility to autoimmune diseases in different populations, such as type 1 diabetes, celiac disease and rheumatoid arthritis." (PMID 29973665, 2018). "Polymorphisms in the promoter −318C/T, exon 1 + 49A/G in the 3′-untranslated region of exons, and CT60 in the CTLA4 gene have been confirmed to be associated with organ-specific autoimmune diseases." (PMID 28133421, 2017). "The genes with such notable patterns include CTLA4, known for its inhibitory role in T cell mediated immune responses and association with many organ-specific autoimmune diseases." (PMID 28248954, 2017). "Deficiency of CTLA-4 in Tregs causes spontaneous development of systemic lymphoproliferation, fatal T cell–mediated autoimmune disease, and hyperproduction of immunoglobulin E in mice." (PMID 28953925, 2017). "The CTLA-4 gene had been previously implicated, in different ethnic groups, in diverse autoimmune disorders, including Addison’s disease, Hashimoto’s thyroiditis, Type 1 diabetes mellitus, multiple sclerosis, and GD." (PMID 27014188, 2016).
autoimmune disease (continued). "It has been reported that SNP rs231775 in CTLA-4 gene is associated with an increased frequency of autoimmune diseases such as Graves’ disease, autoimmune hypothyroidism, type I diabetes, and multiple sclerosis." (PMID 27036622, 2016). "Genetic deficiency in CTLA-4 is lethal in mice due to profound immune dysregulation and autoimmune disease." (PMID 27081086, 2016). "Autoimmune diseases are known to share a common genetic architecture, with some loci, such as CTLA4, PTPN22, and the HLA, conferring susceptibility to multiple autoimmune diseases." (PMID 27680876, 2016). "The interaction between CTLA4 and B7 plays an essential role in regulation of self-tolerance, and hence susceptibility to autoimmune diseases." (PMID 26963610, 2016). "A specific deficiency of CTLA-4 in Tregs results in spontaneous development of systemic lymphoproliferation, fatal T cell-mediated autoimmune disease, and hyperproduction of immunoglobulin E in mice, and it also produces potent tumor immunity." (PMID 27941849, 2016). "Cytotoxic T-Lymphocyte Antigen 4 (CTLA4) is one of the susceptibility genes for various autoimmune diseases." (PMID 26963610, 2016). "In particular, CTLA-4 is important in controlling antigen-specific immunity, including responses to autoantigens associated with autoimmune disease." (PMID 27487771, 2016). "CTLA-4 is a critical gatekeeper of T-cell activation and immunological tolerance and has been implicated in patients with a variety of autoimmune diseases through genetic association." (PMID 27835693, 2016). "Single nucleotide polymorphisms (SNPs) in CTLA-4 are associated with autoimmune diseases such as autoimmune thyroid disease and multiple sclerosis, and play an influential role in graft rejection and the long-term clinical outcome of organ transplantation." (PMID 27081086, 2016). "In contrast to autoimmune diseases; in which the favorable alleles are those associated with higher PD-1 and CTLA-4 levels, polymorphisms associated with diminished CTLA-4 expression in HCV infections were found to correlate to improved viral clearance." (PMID 27100663, 2016). "One such strictly Treg cell-specific epigenetic element was found at the CTLA4 locus, which harbors a risk allele for multiple autoimmune disorders, including rheumatoid arthritis, type 1 diabetes (T1D), Graves' disease, and systemic lupus erythematosus." (PMID 26510014, 2015). "Clinical significance of CTLA-4 agonists was implicated in the context of several autoimmune diseases including CD." (PMID 25756783, 2015). "The SNPs in this block had odd ratios between 2.1 and 2.9 and were ~1.4Mb downstream from CTLA4, a costimulatory molecule expressed by activated T cells that has been linked to a number of autoimmune diseases." (PMID 26379185, 2015). "Single nucleotide polymorphisms (SNPs) in the CTLA4 promoter have been shown to be associated with several autoimmune diseases in humans and more recently with diabetes mellitus and hypoadrenocorticism in dogs." (PMID 26401336, 2015). "The genetic associations between IL-10, TNF/LTA, and CTLA-4 polymorphisms have been investigated extensively in many autoimmune diseases and malignancies, and have been confirmed for certain diseases." (PMID 26108796, 2015). "In humans, single nucleotide polymorphism (SNP) CT60 (rs3087243) in the 3′ untranslated region of human CTLA4 is associated with multiple autoimmune diseases, including type 1 diabetes (T1D), Graves’ disease (GD), rheumatoid arthritis, and celiac disease." (PMID 24928993, 2014). "Further, SNPs of the human CTLA-4 gene have been implicated in the susceptibility to autoimmune disorders such as type I diabetes, rheumatoid arthritis, and multiple sclerosis." (PMID 25538704, 2014). "The two most investigated genes, which are potentially associated with autoimmune diseases are CTLA-4 and PTPN22." (PMID 25452756, 2014).
autoimmune disease (continued). "To date, clinical trials involving cancer immunotherapies, such checkpoint blocking antibodies directed at CTLA-4 (ipilimumab), have excluded patients with underlying autoimmune disease given concern for potential triggering of autoimmune exacerbations." (PMID 25349698, 2014). "Six autoimmune disease-related risk alleles of CTLA4 (rs1863800, rs733618, rs4553808, rs5742909, rs231775, and rs3087243) were investigated for MG in northern Chinese." (PMID 25003519, 2014). "Cytotoxic T lymphocyte-associated antigen-4 (CTLA4), a critical negative regulator of the T-cell response, has been considered a candidate for many autoimmune diseases." (PMID 25003519, 2014). "Polymorphisms of the CTLA4 gene have been shown to confer susceptibility to several autoimmune diseases, due to its role in the down-regulation of the activated immune response." (PMID 24465825, 2014). "There is some doubt about the molecular heterogeneity of sCTLA-4 and the relationship between the ability to produce sCTLA-4 and the CTLA-4 polymorphisms observed in some autoimmune diseases." (PMID 25383768, 2014). "Increasing evidence showed that CTLA-4 gene is an important susceptibility locus for autoimmune disorders." (PMID 24605322, 2014). "A specific polymorphism of CTLA-4 was found to be protective for autoimmune disease, but associated with risk of multiple types of cancer." (PMID 23801991, 2013). "Recent studies showed that mice deficient the CTLA-4 gene were born healthy but died early due to severe lymphoproliferative disorders and autoimmune diseases." (PMID 24376736, 2013). "SNPs in the CD28/CTLA4/ICOS gene region were reported to be associated with several autoimmune diseases including, type-1 diabetes, systemic lupus erythematosus, autoimmune thyroid diseases and celiac disease." (PMID 22911710, 2012). "Pathogenesis of autoimmune disorders in mice with Treg-specific CTLA-4 deficiency demonstrated the importance of CTLA-4 in their regulatory activity." (PMID 22783261, 2012). "In humans, CTLA-4 has been suggested to be associated with various autoimmune diseases including Grave's disease, autoimmune hypothyroidism, type I diabetes, systemic lupus erythematosus (SLE), and celiac disease." (PMID 22997525, 2012). "Several polymorphisms within the CTLA-4 gene have been associated with an increased risk of developing autoimmune diseases and, very recently, with susceptibility to human cancer." (PMID 23049754, 2012). "The CTLA-4 protein acts as a potent negative regulator of T-cell response and variants of CTLA4 have been consistently associated with numerous autoimmune disorders." (PMID 22654555, 2011). "CTLA-4/CD28 gene polymorphisms are genetically associated with several autoimmune diseases such as systemic lupus erythematosus (SLE), Graves’ disease, rheumatoid arthritis and Behçet’s disease." (PMID 25013611, 2011). "Polymorphisms in CTLA4 are associated with a very wide range of inflammatory and autoimmune diseases." (PMID 21637411, 2010). "One of the candidate genes which has a strong association with several autoimmune diseases is CTLA-4 gene located in chromosome 2q33 region." (PMID 20418973, 2010). "The human CTLA-4 gene is located on chromosome 2q33, in a region that is associated with susceptibility for autoimmune disease." (PMID 21044351, 2010). "Polymorphisms in the CTLA4 gene have been associated with autoimmune diseases and the functional CT60 single nucleotide polymorphism (rs3087243, also named 6230G > A) has been proposed to be a casual variant in several of these diseases." (PMID 21637411, 2010). "The association of several autoimmune diseases with the CTLA-4 +49G allele has been explained as the result of a reduced inhibitory function associated with the G allele." (PMID 19568552, 2009). "Specific deficiency of Ctla4-/- in natural Foxp3+CD4+ regulatory T cells results in spontaneous autoimmune disease." (PMID 19951419, 2009).
autoimmune disease (continued). "Human polymorphisms in CTLA4 are associated with several autoimmune diseases, including type 1 diabetes (T1D), Graves' disease, Hashimoto's thyroiditis, celiac disease, and rheumatoid arthritis (RA)." (PMID 19951419, 2009). "Protein tyrosine phosphatase type 22 (PTPN22) and Cytotoxic T lymphocyte antigen-4 (CTLA-4) are two of these genes, and single nucleotide polymorphisms (SNPs) in the genes encoding these molecules have been associated with several autoimmune diseases." (PMID 19180256, 2009). "Extensive population genetics studies have suggested associations between SNPs in and around the CTLA-4 locus on chromosome 2 in man and the presence of autoimmune disease." (PMID 19014504, 2008). "Numerous population genetics studies have documented significant associations between autoimmune diseases and single nucleotide polymorphisms (SNPs) within and around the CTLA-4 region of chromosome 2 in man." (PMID 19014504, 2008). "Increasingly, single nucleotide polymorphisms (SNPs) of the CTLA4 gene are correlated with autoimmune diseases." (PMID 20300303, 2008). "CTLA-4 negative regulation was shown by antibody ligation, and by the development of autoimmune disease in CTLA-4 deficient mice." (PMID 19052636, 2008). "Polymorphisms in CTLA-4, the gene encoding cytotoxic T lymphocyte-associated antigen-4, have been widely studied in connection with genetic susceptibility to various autoimmune diseases, but studies have led to contradictory results in different populations." (PMID 17341301, 2007). "CTLA-4 gene polymorphisms have been widely studied in connection with genetic susceptibility to various autoimmune diseases, but studies have led to contradictory results in different populations." (PMID 17341301, 2007). "Previous studies have extensively examined the association of polymorphisms within CTLA-4 with autoimmune diseases including Graves' disease, type I diabetes, systemic lupus erythematosus, and Hashimoto's thyroiditis, as well as malignancy susceptibility." (PMID 17825114, 2007). "Several reports have indicated that CTLA-4 deficient mice show a severe lymphoproliferative disorder and autoimmune disease with early lethality." (PMID 16259622, 2005). "It should be noted that the genomic region 2q33 linked to autoimmune disease contains cluster of three genes encoding costimulatory molecules CTLA-4, CD28 and inducible costimulator (ICOS)." (PMID 15762980, 2005). "Several studies have demonstrated a genetic association between polymorphisms within or near the CTLA-4 gene and T1D as well as other autoimmune diseases." (PMID 16259622, 2005). "Several genetic variations, e.g., PTPN22 and CTLA-4 polymorphisms, might predispose simultaneously to the development of AD, RA, and other systemic and organ-specific autoimmune diseases." (PMID 40507712, 2025). "Consequently, the CTLA-4 pathway is a critical component of immune-based cancer therapies and treatments for autoimmune diseases and CTLA-4 deficiency." (PMID 40260303, 2025). "Genetic variants in the CTLA-4 locus have been implicated in various autoimmune disorders, suggesting that individual genetic backgrounds may affect the immune response to belatacept." (PMID 40282351, 2025). "In addition to the HLA region, several studies have also explored the involvement of functional variations of the cytotoxic T-lymphocyte-associated antigen 4 (CTLA4) gene in a number of autoimmune disorders." (PMID 38892695, 2024). "The SNPs of CTLA-4-encoding genes are involved in the pathogenesis of many autoimmune diseases." (PMID 38485815, 2024). "Mutations in the CTLA-4 gene may lead to a deficiency in regulatory T-cell downregulation of immune responses, resulting in T-cell hyperactivation and thus triggering autoimmune diseases." (PMID 38352885, 2024). "However, the administration of anti-PD1 and anti-CTLA4 antibodies has been associated with adverse inflammatory responses similar to autoimmune diseases." (PMID 38418707, 2024).